ALG12 (ALG12 alpha-1,6-mannosyltransferase)
Description:
Mannosyltransferase that operates in the biosynthetic pathway of dolichol-linked oligosaccharides, the glycan precursors employed in protein asparagine (N)-glycosylation. The assembly of dolichol-linked oligosaccharides begins on the cytosolic side of the endoplasmic reticulum membrane and finishes in its lumen. The sequential addition of sugars to dolichol pyrophosphate produces dolichol-linked oligosaccharides containing fourteen sugars, including two GlcNAcs, nine mannoses and three glucoses. Once assembled, the oligosaccharide is transferred from the lipid to nascent proteins by oligosaccharyltransferases. In the lumen of the endoplasmic reticulum, adds the eighth mannose residue in an alpha-1,6 linkage onto Man(7)GlcNAc(2)-PP-dolichol to produce Man(8)GlcNAc(2)-PP-dolichol.
Synonyms: hALG12; PP14673; ECM39; CDG1G
Tractability: Antibody: UniProt predicts a signal peptide or a membrane-spanning region.
Gene: Protein-coding gene on chromosome 22 (49,900,229 to 49,918,458, reverse strand). Ensembl gene ENSG00000182858.
Subcellular location: Endoplasmic reticulum membrane
Subcellular location (Human Protein Atlas): Endoplasmic reticulum
Pathways (Reactome):
Disease: Defective ALG12 causes CDG-1g
Metabolism of proteins: Biosynthesis of the N-glycan precursor (dolichol lipid-linked oligosaccharide, LLO) and transfer to a nascent protein
Gene Ontology:
Molecular function: dol-P-Man:Man(7)GlcNAc(2)-PP-Dol alpha-1,6-mannosyltransferase activity; alpha-1,6-mannosyltransferase activity; mannosyltransferase activity; glycosyltransferase activity
Biological process: dolichol-linked oligosaccharide biosynthetic process; protein N-linked glycosylation; protein folding
Cellular component: membrane; endoplasmic reticulum; endoplasmic reticulum membrane; lumenal side of endoplasmic reticulum membrane
Genetic constraint (gnomAD): Loss-of-function variants: 36 observed, 49.25 expected, observed/expected ratio (o/e) 0.73, 90% interval 0.56 to 0.96. The upper end of that interval is the gene's LOEUF score, 0.96, which puts it in group 4 of 6, group 1 being the genes least tolerant of losing a copy. Missense variants: 599 observed, 665.21 expected, observed/expected ratio (o/e) 0.9, 90% interval 0.84 to 0.96. Synonymous variants: 326 observed, 306.52 expected, observed/expected ratio (o/e) 1.06, 90% interval 0.97 to 1.17.
Gene-disease validity (ClinGen):
ClinGen rates the evidence that ALG12 causes each of these diseases.
ALG12-congenital disorder of glycosylation (autosomal recessive): Definitive.
Homologues: Orthologues: chimpanzee ALG12 (98% identical), macaque ALG12 (96% identical), guinea pig ALG12 (82% identical), rat Alg12 (80% identical), mouse Alg12 (79% identical), pig ALG12 (78% identical), rabbit ALG12 (77% identical), dog ALG12 (71% identical), tropical clawed frog alg12 (64% identical), zebrafish alg12 (59% identical), Drosophila melanogaster Alg12 (47% identical), Caenorhabditis elegans algn-12 (36% identical). Paralogues in human: PIGB (23% identical), ALG9 (18% identical).
Diseases named in the same sentence as ALG12 in open-access papers:
ALG12 is named in the same sentence as 27 diseases in open-access papers, as found by Europe PMC text mining. Sharing a sentence is not in itself a finding about the gene and the disease. The quoted sentences say what the papers report.
melanoma (2 papers, 2016 to 2021). A malignant, usually aggressive tumor composed of atypical, neoplastic melanocytes. "In addition, we identify five genes (ALG12, GUSB, RPLP0, KRBA2, and ADAT2) that are stably expressed in melanoma cells independent of the presence of T cells or the T cell-derived cytokines IFNγ and TNFα." (PMID 27625650, 2016).
breast carcinoma (1 paper, 2021). "Expression levels of ALG1, ALG2, ALG3, ALG8, ALG9, ALG12 and ALG13 were differentially upregulated in radioresistant breast cancer tissues compared with those in radiosensitive tissues, particularly ALG3 with the highest level (4.53-fold change)." (PMID 33931075, 2021).
cataract (1 paper, 2015). Partial or complete opacity of the crystalline lens of one or both eyes that decreases visual acuity and eventually results in blindness. "Unlike other CDG types, cataracts (ocular findings) have only been reported in ALG8-CDG, ALG12-CDG, other subtypes in early LLO synthesis (like SRD5A3-CDG) and some unclassified CDG." (PMID 26066342, 2015).
Failure to thrive (1 paper, 2025). Failure to thrive (FTT) refers to a child whose physical growth is substantially below the norm. "Mutations in ALG12 disrupt this process, leading to defective glycosylation and causing congenital disorder of glycosylation type Ig (CDG-Ig), a multisystemic condition characterized by GDD, ID, hypotonia, seizures, and failure to thrive." (PMID 40243517, 2025).
gastroesophageal reflux (1 paper, 2022). "Dysphagia and/or gastroesophageal reflux was present in ALG1‐, ALG6‐, ALG11‐, ALG12‐, DPM1‐, and DOLK‐CDG." (PMID 35279850, 2022).
hypogammaglobulinemia (1 paper, 2024). "ALG12-, ATP6AP1-, and MOGS-CDG fall within as the category of predominantly antibody deficiencies since all of them present hypogammaglobulinemia, with low IgG levels." (PMID 38550576, 2024). "The hypogammaglobulinemia reported in ALG12- and MOGS-CDG patients translates into propensity for recurrent and severe bacterial infections due affected antibody-mediate immune processes." (PMID 38550576, 2024). "Consequently, this likely contributes to the genesis of the antibody deficiency, inflammatory episodes and absent responses to vaccines observed in ALG12-, MOGS-, and ATP6AP1-CDG." (PMID 38550576, 2024).
Hypoglycemia (1 paper, 2020). A decreased concentration of glucose in the blood. "Other CDG in which hypoglycemia has been reported are DOLK‐CDG, ALG6‐CDG, ALG3‐CDG, and ALG12‐CDG." (PMID 32071842, 2020).
ovarian carcinoma (1 paper, 2022). A malignant neoplasm originating from the surface ovarian epithelium. "To gain insight into changes in mannosyltransferases (ALGs), which have been found (ALG1, ALG2, ALG3, ALG9, ALG11 and ALG12) in ovarian cancer, we queried publicly available transcriptomic data, including Gene Expression Omnibus (GEO, GSE18520) and The Cancer Genome Atlas (TCGA) datasets." (PMID 36231102, 2022).
Seizure (1 paper, 2022). A seizure is an intermittent abnormality of nervous system physiology characterized by a transient occurrence of signs and/or symptoms due to abnormal excessive or synchronous neuronal activity in the brain. "Seizures were present in most CDG patients, except in those with ALG12‐, DPM3‐, SRD5A3‐, and DPAGT‐CDG." (PMID 35279850, 2022).
cancer (2 papers, 2019 to 2023). A tumor composed of atypical neoplastic, often pleomorphic cells that invade other tissues. "Interestingly, most of these genes are linked with cancer processes (Pld1, Fam13c, Svbp, TMem192, Zc3h7a, RTP4, Naa30, Zgrf1, Slc33a1, Dnmt3b, Map6, Plin4, Eps8L2, Alg12, Capg and Tdp2)." (PMID 37700325, 2023). "Loss-of-function ALG12 mutations cause ALG12-congenital disorder of glycosylation, but this gene has not been previously associated with cancer." (PMID 31870430, 2019).
skeletal dysplasia (2 papers, 2021). Any Mendelian diseases that affects growth and development of the skeleton. "Contrary to PMM2-CDG, skeletal dysplasia was well characterized in other CDGs, including ALG12-CDG, ALG3-CDG, ALG9-CDG, ALG6-CDG, PGM3-CDG, CSGALNACT1-CDG, SLC35D1-CDG and TMEM165-CDG." (PMID 34441372, 2021). "In some of them (ALG12-CDG, ALG3-CDG, ALG9-CDG, PGM3-CDG, SLC35D1-CDG), a severe prenatal-onset skeletal dysplasia was observed and associated with an early death." (PMID 34441372, 2021). "There is a group of CDGs, including ALG12-CDG, ALG3-CDG, ALG9-CDG, ALG6-CDG, PGM3-CDG, CSGALNACT1-CDG, SLC35D1-CDG, and TMEM-165 with well-defined skeletal dysplasia." (PMID 34441372, 2021). "Contrary to PMM2-CDG, all remaining CDG, including ALG12-CDG, ALG3-CDG, ALG9-CDG, ALG6-CDG, PGM3-CDG, CSGALNACT1-CDG, SLC35D1-CDG and TMEM-165, are characterized by well-defined skeletal dysplasia." (PMID 34441372, 2021). "Some types of CDG, including ALG3-CDG, ALG6-CDG, ALG9-CDG, ALG12-CDG, PGM3-CDG, CSGALNACT1-CDG, SLC35D1-CDG, and TMEM-165, were reported with well-defined skeletal dysplasia." (PMID 34540767, 2021).
infection (1 paper, 2022). The state of being infected such as from the introduction of a foreign agent such as serum, vaccine, antigenic substance or organism. "The C. neoformansALG3, ALG9, and ALG12 deletion mutant strains, generating truncated core N-glycans, do not show defects in early stages of host cell interaction during infection, including attachment to lung epithelial cells, opsonic/nonopsonic phagocytosis, and phagosome maturation." (PMID 36409123, 2022).
ALG12 also shares sentences with these, for which no sentence is quoted: epilepsy (3 papers); cerebral palsy (1); coagulation disorders (1); congenital disorder of glycosylation (1); epileptic encephalopathies (1); fructose intolerance (1); glioma (1); hydrops (1); Immunodeficiency (1); Intellectual disability (1); lymphoma (1); Roifman syndrome (1); syndromic epilepsy (1); Taybi syndrome (1); tumour (1).